RPS10P3 (ribosomal protein S10 pseudogene 3)
Synonyms: RPS10_10_994
Gene: Processed pseudogene on chromosome 9 (88,016,300 to 88,016,793, forward strand). Ensembl gene ENSG00000217716.
Diseases named in the same sentence as RPS10P3 in open-access papers:
RPS10P3 is named in the same sentence as 1 disease in open-access papers, as found by Europe PMC text mining. Sharing a sentence is not in itself a finding about the gene and the disease.
RPS10P3 shares sentences with these, for which no sentence is quoted: psychosis (1 paper).